SOX2 (SRY-box transcription factor 2)
Diseases named in the same sentence as SOX2 in open-access papers (continued):
Sharing a sentence is not in itself a finding about the gene and the disease.
colon carcinoma (continued). "It was observed that ROR played as a ceRNA to modulate Oct4, Sox2 and Nanog expression by sponging miR-145 in colonic cancer stem cell." (PMID 31889903, 2019). "The stemness of colon cancer stem cells were found to be associated with higher expression of CD133, ALDH, NANOG, OCT4 and SOX-2, and these markers are found connected to the drug resistance of cancer cells." (PMID 31349708, 2019). "High expression of SOX2 is correlated with a poor prognosis, relapse, and lower survival of patients with colon cancer." (PMID 29564063, 2018). "Correspondingly, the expression levels of stem cell-associated genes, including OCT4, Lin28, Lgr5, KLF, Bmi-1, CD44 and SOX2, increased sharply in colon cancer cells upon treatment with exosomes from BM-MSCs or exosomal miR-142-3p." (PMID 30220706, 2018). "Sox2 expression was measured in colon cancer cells and colorectal clinical samples by qRT-PCR and western blot analysis." (PMID 30518951, 2018). "In western blot analyses, colon cancer cell lines generally expressed the Sox2 protein at levels comparable to positive control MCF7 and U87 cells." (PMID 30518951, 2018). "Because CSCs are thought to exist as a minimal population relative to the whole tumor, we postulated that the colon cancer cells actively producing Sox2 mRNA retain CSC-like properties, such as resistance to chemotherapy and asymmetric cell division." (PMID 30518951, 2018). "We also found increased expression of stem cell markers, including OCT4, Lin28, KLF, Bmi-1, CD44 and SOX2, in colon cancer cells upon treatment with BM-MSCs-derived exosomes." (PMID 30220706, 2018). "In this study, we found that colon cancer cells express considerable levels of the Sox2 protein, comparable to the MCF7 and U87 cells used as positive controls." (PMID 30518951, 2018). "Increased CD133 and stemness-associated protein levels (β-catenin, Oct4, Sox2, and Nanog) and enhanced sphere size/formation (self-renewal) suggest that DEHP/MEHP treatment promotes colon cancer cell stemness." (PMID 29568348, 2018). "To explore the potential function of Sox2 in the proliferative activity of colon cancer cells, we treated Caco2 cells that retain relatively high Sox2 protein expression with small interfering RNA (siRNA) in vitro." (PMID 30518951, 2018). "Accordingly, we here have shown that the treatment with AEE788, specially when combined with celecoxib, significantly reduced the expression of Oct 3/4, Nanog and Sox-2 in colon cancer cells." (PMID 26107817, 2015). "Transcriptional regulator SOX2 was identified as an oncogene in many cancers, including colon cancer." (PMID 25868860, 2015). "Previous studies have shown that reprogramming of colon cancer cells using Oct3/4, Sox2, Klf4, and cMyc reduces cancer malignancy." (PMID 25970424, 2015). "Cancer-related gene c-MYC promoter was validated to combine with CD44 in colon cancer stem cells; SOX2 was chosen for its indispensable position in various CSCs." (PMID 26540347, 2015). "The expression profile of stem cell and CSC markers genes of BORIS-depleted spheres showed that NANOG, OCT4 and SOX2 genes were down-regulated in both breast and colon tumor cells." (PMID 26185996, 2015). "The transcription factor SOX2 is involved together with c-MYC, KLF4 and OCT3/4 in the induction and maintenance of pluripotent stem cells and has been also associated the expression of both SOX2 and β-CATENIN with metastases and poor prognosis in colon cancer." (PMID 24946763, 2014). "Taken together, our results demonstrated that regulation of autophagy mediated by Sox2 is a mechanism-driven novel strategy to treat human colon cancers." (PMID 23451179, 2013).
colon carcinoma (continued). "Because PRMT8 is highly expressed in colon cancer stem cells, it may be able to influence the expression of Oct4 and Nanog multipotent transcription factors by preventing Sox2 degradation and raising Sox2 protein content through Sox2 methylation." (PMID 41154773, 2025). "We confirmed strong nuclear expression of the SOX2 protein in S and AS mouse primary colon tumors and organoids where the Sox9 gene is inactive, whereas only approximately 5% of cells in tissues from A mice showed weakly positive SOX2 staining." (PMID 40179020, 2025). "Interestingly, other transcription factors including KLF4, OCT4, and SOX2 were unaffected by c-Fos in colon cancer cells." (PMID 38233377, 2024). "Wnt signaling has been reported to regulate EMT through β-catenin/SOX2 in colon cancer." (PMID 38057816, 2023). "Furthermore, the mRNA levels of c‐Myc, Bmi‐1, and Sox‐2, which are considered to be oncogenic in the colon cancer, were reduced by SIRT1 siRNA." (PMID 34826187, 2022). "It has been demonstrated that NB could block spleen and liver metastasis in mouse model of colon cancer and also inhibit signaling pathways such as Nanog, sex-determining region Y-box protein 2 (Sox2), c-Myc, and β-catenin." (PMID 36180880, 2022). "Recent study has reported that NB could inhibit metastasis in mouse model of colon cancer and also decrease CSCs related molecules such as Nanog, sex-determining region Y-box protein 2 (Sox2), c-Myc, and β-catenin." (PMID 36180880, 2022). "Interestingly, a recent study showed that the SOX2 gene promoter was directly repressed from vitamin D receptor (VDR) occupancy on VDR elements in colon cancer cells." (PMID 34503224, 2021). "CD44v6 is a biomarker associated with colon cancer stemness and tumor progression, and hyaluronan-engaged CD44v3 induces the expression of stem cell markers, NANOG, SOX2, and OCT4, promoting tumor progression and chemoresistance of head and neck squamous cell carcinomas." (PMID 33804427, 2021). "The role of SOX2 in colon cancer treatment resistance will need to be examined in future work." (PMID 33322770, 2020). "Taken together, these findings strongly suggest that the Sox2+ colon cancer cells behave like CSCs." (PMID 30518951, 2018). "Colon cancer cell lines and colorectal tumor tissues generally expressed the Sox2 protein." (PMID 30518951, 2018). "In addition, we found increased expression of stem cell markers, including OCT4, Lin28, KLF, Bmi-1, CD44 and SOX2, in colon cancer cells upon treatment of BM-MSC-derived exosomes." (PMID 30220706, 2018). "To monitor these cells, we constructed a fluorescence cell visualization system in response to Sox2 promoter activation and tried to elucidate whether Sox2 may drive CSCs in colon cancer." (PMID 30518951, 2018). "Most colon cancer cells may fundamentally retain Sox2 protein expression; however, real CSCs are thought to exist in a small population." (PMID 30518951, 2018). "SOX2 as a member of the SOX gene family is expressed in human colon cancer." (PMID 29564063, 2018). "Sox2 expression induced autophagy in all colon cancer cell lines examined." (PMID 23451179, 2013). "Although the molecular mechanism explaining how Sox2 modulates PTEN phosphorylation is not clearly understood, our results suggested that Sox2-induced autophagy might be applicable in suppressing colon cancer." (PMID 23451179, 2013). "Notably, knocking down ATG10 restores cancer cell properties in Sox2-expressing colon cancer cells." (PMID 38397988, 2024). "Tumor spheroid models derived from sporadic colon cancer cell lines have been utilized to identify stem cell specific molecular markers including octamer binding transcription factor-4 (Oct-4), Kruppel-like factor-4 (Klf-4), sex determining region Y-box-2 (SOX-2) and cellular Myc (c-Myc)." (PMID 35269660, 2022).
colon carcinoma (continued). "Besides Sox2 and ALDH, expression of several other surface proteins, such as CD44, CD133, Lgr5, CD24, EpCAM and ABCG2, has been associated with stemness features in the context of colon cancer." (PMID 32927726, 2020). "Notably, knockdown of ATG10 in Sox2-expressing colon cancer cells restored cancer cell properties." (PMID 23451179, 2013). "Here, we found that Sox2, a key transcription factor in the regulation of the “stemness” of embryonic stem cells and induced-pluripotent stem cells, strongly induced autophagic phenomena, including intracellular vacuole formation and lysosomal activation in colon cancer cells." (PMID 23451179, 2013). "Compared with effects of Apc inactivation in mouse colon tumors, combined Apc and Sox9 inactivation instigated more invasive tumors with epithelial-mesenchymal transition (EMT) and SOX2 stem cell factor upregulation." (PMID 40179020, 2025). "H3K36me2, expressions of multiple oncogenes (ADAM9, EGFR, Sox2, Bcl-2, SYK, and MET) and Akt activation were significantly decreased after NSD2 silencing or knockout in primary colon cancer cells." (PMID 34671018, 2021). "Consistently higher expression of CD133, SOX2, NANOG, OCT4, CD44 and Lgr5 in ALDH+ cells, which was the representative markers of CSC, validated the truth of stemness of ALDH+ colon cancer cells." (PMID 30962766, 2019). "In fact, the tumor sphere formation ability was decreased, and the levels of a panel of established CSC markers, including CD133, CD44, Sox2, Oct4, Nanog, and ALDH1A1, were decreased in colon cancer cells treated with GM‐Exo subjected to S100A9 knockdown." (PMID 31559140, 2019). "We also assessed stemness-related protein expression (β-catenin, Oct4, Sox2, and Nanog) and self-renewal in DEHP/MEHP-treated colon cancer cells." (PMID 29568348, 2018). "YAP1 regulates the expression of SOX2 and c-MYC, which are overexpressed in colon cancer and promote metastasis and tumor growth." (PMID 29416778, 2018). "Previous studies have shown that the colon cancer stem cells isolated from HCT116 cells express high levels of PROM1 (CD133), CD44, EPCAM, SOX2, c-MYC, and NANOG." (PMID 29507661, 2018). "In the present study, we show that colon cancer cell lines and clinical CRC samples frequently express basal levels of the Sox2 protein." (PMID 30518951, 2018). "In colon cancer, DOT1L increases cancer stemness and tumorigenic potential by inducing the core stem cell genes NANOG, SOX2 and Pou5F1." (PMID 27581651, 2016). "We transduced OCT3/4, SOX2, KLF4, or a mixture of the three (hereafter, OSK) into the SW480 human colon cancer cell line using retrovirus vectors, and also a Mock vector (empty vector) was used as a control." (PMID 25006808, 2014). "In the current study, we transduced OCT3/4, SOX2 and KLF4 into human colon cancer cells under the parental cell culture conditions and analyzed the transduced cells in terms of their CSC properties in vitro and in vivo." (PMID 25006808, 2014). "In summary, we generated the cells with CSC properties: iCSCs, by introducing OCT3/4, SOX2 and KLF4 in the SW480 colon cancer cell line, and were able to isolate an iCSCs-enriched cell population by using Hoechst33342 staining and VM treatment." (PMID 25006808, 2014). "We retrovirally introduced a set of defined factors (OCT3/4, SOX2 and KLF4) into human colon cancer cells, followed by culture with conventional serum-containing medium, not human embryonic stem cell medium." (PMID 25006808, 2014). "For sake of comparison, the established GBM-derived cell line U87 (Sox2-negative) and the colon carcinoma cell line CaCo2 were included (CaCo2 cells are CD133-positive)." (PMID 38306361, 2024).
colon carcinoma (continued). "It is suggested that TP5 may inhibit the self-renewal and tumorigenesis of colon cancer stem cells by regulating the important stemness genes ALDH1, SOX-2, OCT-4, and Nanog." (PMID 35242031, 2022). "Secondly, CD24, CD44 and CD133 are specific surface markers that can be expressed by colon cancer stem cells; ALDH1, OCT4, SOX2 and Nanog are all markers of stemness status of cancer stem cells, which are important for maintaining the nature and drug resistance of cancer stem cells." (PMID 35242031, 2022). "Moreover, western blot and qRT-PCR results showed BCAR4high cells showed higher expression of NANOG, OCT4, SOX2, CD44, CD133 and Lgr5 which are important markers of CSC in colon cancer." (PMID 30962766, 2019). "Knockdown of STRA6 or RBP4 in SW480 colon carcinoma cells decreased the levels of NANOG and SOX2." (PMID 28689994, 2017). "Our study with mouse colon cancer cell lines also clearly showed that overexpression of SOX2 led to increased expression of mesenchymal markers (vimentin and N-cadherin) and EMT-inducing transcription factors (e.g., TWIST1), supporting its role in promoting EMT in colon cancer." (PMID 40179020, 2025). "We found SOX2 was expressed in 13% of 92 independent colon tumors obtained from 10 AKP mice, but not in adjacent normal colon epithelium, and SOX2 expression was linked to high tumor grade (P < 0.0001) and invasiveness (P < 0.0001), suggesting a role for increased SOX2 in mouse CRC progression." (PMID 40179020, 2025). "Similarly, in human colon cancer, a set of TFs such as OCT3/4, SOX2 and KLF4 could transform colon cancer cells into CSCs." (PMID 29799161, 2018). "Interestingly, it was previously demonstrated that Sox21 is induced by Sox2, and, unlike Sox2, Sox21 negatively regulates transcription of Cdx2 in mES and colon cancer cells." (PMID 26783396, 2015). "To investigate whether Sox2 overexpression can induce vacuole formation in different colon cancer cell lines, we transduced lenti-Sox2 viral particles into CCD-18Co normal colon cells and HCT116, HT29 and WiDr human colon cancer cells." (PMID 23451179, 2013). "Our results uncovered that NANOG, rather than KLF4, OCT4, and SOX2, was significantly up-regulated in FOS-overexpressed colon cancer cells." (PMID 38233377, 2024). "We next analyzed in colon cancer cells the expression of LGR5, NANOG, OCT-4, and SOX2 in the presence and absence of α1-PDX." (PMID 35267511, 2022). "Moreover, although there may have been differences in reactivities between human and mouse antibodies, SOX2 protein expression in sphere-forming cells from HRASV12-expressing MEFs was not significantly different from that observed in the human colon cancer line HCT116." (PMID 35190631, 2022). "In the present study, we found that TP5 can directly inhibit cultured colon cancer stem cells in medium without serum, and reduce the expression of cancer stem cell markers: CD44, CD24 and CD133, and stem-cell related genes: ALDH2, SOX2, OCT4 and Nanog." (PMID 35242031, 2022). "We also tested the impact of LINC01287 on stemness of colon cancer cells, but unfortunately LINC01287 knockdown showed no influence on the expression levels of stemness markers such as Oct4, Lin28, Nanog and Sox2." (PMID 34229645, 2021). "Similarly, suppression of endogenous TMPRSS4 reduced ALDH activity in HT-29 and HCT-116 colon cancer cells, and this was accompanied by downregulation of SLUG, TWIST1, and SOX2, but not BMI1 or CD133." (PMID 34809669, 2021).
cervical cancer (74 papers, 2012 to 2025). A primary or metastatic malignant neoplasm involving the cervix. "High SOX2 expression in cervical cancer tissues was associated with radiation resistance of patients." (PMID 40083005, 2025). "Previous studies have found that miR-122-5p can bind to SOX2, and miR-122-5p-mediated down-regulation of SOX2 is associated with cervical cancer." (PMID 38617751, 2024). "Another study found that high SRY-box transcription factor 2 (SOX2) expression causes radioresistance in cervical cancer, indicating that SOX2 is closely associated with changes in irradiation-induced survival, proliferation, apoptosis, and cell cycle." (PMID 38020914, 2023). "OCT4 and SOX2 expression have been shown to be independent prognostic factors in cervical cancer, with OCT4 associated with poorly differentiated tumours and advanced stage disease, and SOX2 associated with poor overall survival and recurrence." (PMID 34283069, 2021). "In their study, they showed that OCT4 overexpression and loss of SOX2 expression of tumor parts were strongly associated with poor prognosis of patients with cervical cancer." (PMID 30150594, 2018). "It is worth mentioning that in cervical SCCs a high expression of SOX2 has been reported; however, the loss of SOX2 in a subgroup of cervical cancer cases, has been associated with poor prognosis." (PMID 28678184, 2017). "Gene analysis has identified SOX2 and TP63 gene expression as important in defining molecular subtypes in HPV related head and neck cancer and SOX2 has been associated with a number of other human cancers including cervical cancer." (PMID 25531390, 2014). "Since 3q26 copy number gains are a frequently occurring mutation in cervical carcinomas, it might be involved in the (over)expression of SOX2 and ultimately lead to the establishment of a stem-like, tumor-initiating cell phenotype." (PMID 35945296, 2022). "In addition, SOX2 overexpression in cervical cancer cell lines causes an increase in proliferation, clonogenicity and tumorigenicity." (PMID 28678184, 2017). "However, in the current cancer tissue samples, OCT4 and SOX2 were associated with opposite effects on survival and lose their association in cervical cancer, as well." (PMID 26706028, 2015). "OCT4 overexpression and loss of SOX2 expression are strongly associated with a poor prognosis in patients with cervical cancer, an effect that may be attributed to structural changes of the extracellular matrix of these tissues that becomes more submissive to the invasion of cancer cells." (PMID 37190092, 2023). "Furthermore, SOX2 expression has been associated with early events of cervical carcinogenesis, since it is highly expressed in premalignant lesions, as well as in cervical cancer, while its expression is low in normal cervical epithelium." (PMID 28678184, 2017). "miR-122-5p can suppress the self-renewal capacity of cervical cancer stem cells by targeting the 3′UTR of SOX2, thereby significantly diminishing their self-renewal potential." (PMID 40710326, 2025). "The interplay between miR-122-5p and UCA1 affects the self-renewal and tumor advancement of cervical cancer stem cells through the modulation of SOX2 expression." (PMID 40710326, 2025). "The overexpression of miR-130b-5p functioned as a tumor suppressor in cervical cancer by targeting ELK1, diminishing the self-renewal capacity of cervical cancer stem cells and lowering the expression of stemness-associated proteins (OCT4, Sox2, and Nanog)." (PMID 40710326, 2025). "In cervical cancer, SOX2 plays a crucial role in promoting the formation of tumor spheres, and its expression is significantly correlated with the prognosis of cervical squamous cell carcinoma." (PMID 39976818, 2025). "In patients with vulvar or cervical cancer, 2-11.4% of CTCs were positive for SOX2 before therapy (light grey dots)." (PMID 40083005, 2025).